CTLA4 (cytotoxic T-lymphocyte associated protein 4)
Diseases named in the same sentence as CTLA4 in open-access papers (continued):
Sharing a sentence is not in itself a finding about the gene and the disease.
melanoma (continued). "In the past decades, immune checkpoint inhibitor therapy targeting cytotoxic T-lymphocyte antigen 4 (CTLA-4), programmed cell death receptor 1 (PD-1), and programmed cell death ligand 1 (PD-L1) have resulted in impressive outcomes in patients with malignant melanoma." (PMID 34025664, 2021). "We have previously reported the utility of CTLA4 promoter methylation as a predictive biomarker for response to immunotherapy and survival in a heterogeneous cohort comprised of N = 50 melanoma patients who received anti-PD-1 and anti-CTLA-4 single-agent or combination immunotherapy." (PMID 33196890, 2021). "There were three retrospective studies of anti-CTLA-4 therapy for melanoma patients with AID." (PMID 33692958, 2021). "In addition, we also found the abundance of the B cell demonstrated positive correlation with ICB response for UC patients, and also achieved preferable predictive performance in ccRCC and in melanoma patients treated with anti-CTLA-4 therapy." (PMID 33915876, 2021). "Reports about sCD25 and ICIs concern mostly CTLA-4-blockade and melanoma patients." (PMID 34359602, 2021). "A retrospective analysis of 50 tumor samples from melanoma patients treated with the anti-CTLA4 antibody ipilimumab provided the first evidence that gene expression profiling could be useful as a predictive biomarker." (PMID 32767058, 2021). "Similarly, in a melanoma mouse model, CTLA-4 blockade cooperated with radiotherapy to increase the CD8 effector T cell to Treg ratio and diversify the T cell receptor (TCR) repertoire resulting in therapeutic synergy." (PMID 34733287, 2021). "After the initial success in melanoma, anti-CTLA-4 antibodies like ipilimumab were tested in solid tumors such as breast cancer with limited efficacy, though it has been recently approved for the treatment of lung cancer in combination with the anti-PD1 antibody nivolumab in advanced NSCLC." (PMID 33466674, 2021). "The results suggested that MAP2K1/2 mutations might be an independent predictor for a favourable clinical response to anti-CTLA4 therapy in patients with melanoma." (PMID 35069558, 2021). "In addition, higher densities of tumour-infiltrating B cells and TLSs were found in a group of melanoma patients receiving neoadjuvant therapy with anti-CTLA-4/anti-PD-1 antibodies in combination." (PMID 34367148, 2021). "We can hypothesize that the wound healing-dependent activation of immune response in cryo-ablated tumour tissue can synergize with immune checkpoint inhibition such as anti-CTLA-4/ipilimumab therapy of melanoma." (PMID 34281259, 2021). "Ipilimumab, a fully human IgG1 anti-CTLA-4 antibody, has been approved as a monotherapy for the treatment of advanced malignant melanoma and together with anti-PD-1 mAb, nivolumab, for the treatment of metastatic melanoma, renal cell carcinoma and metastatic colorectal cancer." (PMID 35069536, 2021). "In addition to monotherapy toxicity, emerging evidence suggests that clinical responses in EOC are less than those seen with CTLA-4 blockade in melanoma, pointing to the need for alternative approaches." (PMID 33322601, 2020). "The effectiveness of immune checkpoint inhibitors (cytotoxic T-lymphocyte-associated antigen 4 (CTLA-4) and programmed death 1 (PD-1)) and targeted therapies (BRAF–MEK inhibitors) in melanoma patients with brain metastases have made a significant change in melanoma treatment." (PMID 33282420, 2020). "Anti-MARCO immunotherapy could synergistically enhance the effect of checkpoint inhibitor (anti-CTLA4) in B16 melanoma models." (PMID 32756500, 2020). "Moreover, an enhanced frequency of melanoma-infiltrating ICOS+ CD4+ T cells, sustained over 3 months of anti-CTLA-4 treatment, was associated with better OS." (PMID 32194568, 2020). "Combination of PD-1 and CTLA-4 blockade reduced macrophage infiltration in B16 melanomas 103,124." (PMID 32194848, 2020).
melanoma (continued). "In addition to its efficacy in the treatment of melanoma, nivolumab has been shown to exhibit a therapeutic benefit against a wider spectrum of cancers than anti-CTLA-4 immune checkpoint inhibitors." (PMID 32349280, 2020). "Nowadays, the anti-CTLA4 ipilimumab (Bristol-Meyers Squibb), the anti-PD-1 nivolumab (Bristol-Meyers Squibb), pembrolizumab (Merck), and the anti-PD-L1 atezolizumab (Roche) are approved for the treatment of numerous cancers (e.g., melanoma, NSCLC, RCC)." (PMID 32244396, 2020). "Furthermore, Ipilimumab and CTLA-4-positive melanoma cell interaction also led to TNF-α release by NK cells." (PMID 32117298, 2020). "Here a total of 160 patients with advanced melanoma or non-small-cell lung cancer (NSCLC), treated with anti-cytotoxic T-lymphocyte-associated protein 4 (anti-CTLA-4) or anti-programmed cell death 1 (anti-PD-1), were divided into five discovery and cross-validation cohorts." (PMID 33427690, 2020). "Moreover, a booster vaccination plus combinational treatment with CD40 stimulation and CTLA-4 inhibition resulted in complete tumor regression in a murine melanoma model." (PMID 31911758, 2020). "Antibodies against CTLA-4 and PD-1/PD-L1 have shown to improve overall survival in many patients with different types of cancer including melanoma, non-small cell lung cancer (NSCLC), renal cell carcinoma, hepatocellular carcinoma, head and neck squamous cell carcinoma and bladder cancer." (PMID 32944086, 2020). "In 2011, the FDA approved CTLA-4 antibodies as therapeutic agents for malignant melanoma." (PMID 31900651, 2020). "Therapeutic options for patients with advanced-stage melanoma have been increased in the last years, and approval of new therapeutic agents such as the checkpoint inhibitors (anti-CTLA4 and anti-PD1 antibodies) and BRAF/MEK inhibitors has opened new expectations for survival." (PMID 32486190, 2020). "Analysis of patient samples suggested a role for ICOS in the activity of anti-CTLA-4 therapy, including in melanoma patients treated with ipilumumab, where a sustained increase in the frequency of ICOS hi CD4+ T cells correlated with clinical benefit and improved survival." (PMID 32970735, 2020). "Clinical application of targeted therapy (BRAF inhibitors with or without MEK inhibitors) and immunotherapy (PD-1 inhibitors and CTLA-4 inhibitors) improve the survival of patients with unresectable melanoma, but the principal therapy for localized melanoma is surgical eradication." (PMID 32708762, 2020). "Since CTLA-4 mAbs has been approved for immunotherapy of melanoma and is in clinical trial for combination with PD-1 mAbs our data suggest combination of IL36 with CTLA-4 mAbs might be of clinical significance to further increase its efficacy." (PMID 32351508, 2020). "For example, an increased frequency of IFN-γ pathway gene mutations in tumors of melanoma patients that did not respond to the anti-CTLA-4 antibody ipilimumab has been shown." (PMID 35582229, 2020). "Also, fecal transplant studies from humans to GF mice show that treatment of melanoma with the CTLA-4 blockade favors outgrowth of B. fragilis in the colon." (PMID 32944086, 2020). "Likewise, IS score, derived from 105 genes based on response to anti-CTLA-4 treatment in melanoma patients, was lower in the ARID1A-low group." (PMID 32878261, 2020). "Indeed, CTLA-4 blockade facilitates tumor infiltration by CD8+ CTLs in melanoma, the first disease for which CTLA-4 blockade obtained FDA approval." (PMID 32922404, 2020). "In the support of this hypothesis, melanoma responders to anti-CTLA-4 therapy were shown to produce T-cells that are specific for neoantigens related to tumor somatic mutations." (PMID 32992737, 2020). "The CTLA-4 immune checkpoint provided the first target for the treatment of advanced melanoma." (PMID 33162990, 2020).
melanoma (continued). "Cancer immunotherapy via immune-checkpoint inhibition (ICI) by antibodies against cytotoxic T-lymphocyte-associated protein 4 (CTLA-4) and cell death protein 1 (PD-1) have significantly improved the outcome of metastasized melanoma and of a rapidly increasing number of other cancer types." (PMID 32290812, 2020). "In both anti-CTLA-4-treated and anti-PD-1-treated patients with melanoma, increases in intratumoral T cells while on treatment were associated with clinical activity, while a higher proximity of CD68+ myeloid cells to CD8+ T cells was documented in non-responders to anti-PD-1." (PMID 33268350, 2020). "Furthermore, a strikingly consistent set of neutrophil enrichments was observed in melanoma tumors failing to respond to either anti-CTLA-4 or anti-PD-1 therapy across three independent published cohorts." (PMID 32296058, 2020). "In the CheckMate 069 (phase II) and CheckMate 067 (phase III) studies for malignant melanoma patients, combination therapy with ipilimumab (human CTLA-4 antibody) and nivolumab significantly prolonged PFS compared with each alone, resulting in FDA approval of this combination therapy." (PMID 31900651, 2020). "Anti-PD1 and anti-CTLA4 therapies have been used to boost antitumor immune responses and have provided significant improvements in outcomes for various cancers, particularly advanced melanomas." (PMID 32652004, 2020). "Indeed, treatment with EpCAM/CD3-bAb in a murine melanoma model resulted in upregulation of the immune checkpoint molecule CTLA-4 on recruited T cells in vivo and CTLA-4 blockade enhanced the humoral antimelanoma response with moderate survival benefit." (PMID 32438548, 2020). "Clinical studies have shown that the effect of treatment in patients with advanced melanoma could be improved when combined with the anti-PD-1/PD-L1 antibody and the CTLA-4 inhibitor." (PMID 33282564, 2020). "Pre-existing CD8+ TILs localized in the invasive tumor margin were predictive of melanoma response to PD-1 or CTLA-4 inhibitor therapy, whereas PD-L1+ melanocytes located next to TILs was shown to lead to the secretion of interferon-gamma as a form of adaptive immune resistance." (PMID 31952311, 2020). "For instance, in a follow up report of the CheckMate067 (phase III trial), a significant improvement in overall survival and objective response rate was observed in advanced melanoma patients treated with nivolumab (PD-1 antibody) plus ipilimumab (CTLA-4 antibody) compare to each monotherapy." (PMID 32645977, 2020). "It should be cautioned that our primary criteria were based on the database of melanoma patients as we are constrained by the fact that clinical efficacy of monotherapy targeting of CTLA-4 has been proven through phase III clinical trials only for this indication." (PMID 31991588, 2020). "We further evaluated whether ISV + α-CTLA-4-induced immune memory could reject brain engraftment of the more aggressive parental B16 (GD2-) melanoma cells." (PMID 32690669, 2020). "Similarly, melanoma patients with increased abundance of Bacteroidaceae, Rikenellaceae, and Barnesiellaceae members responded better to CTLA-4 antibodies." (PMID 32817793, 2020). "In melanomas, it was shown that PD-1, PD-L1, and CTLA-4 signaling might be responsible for tumor intrinsic cell proliferation, survival, growth, and metastatic signals, in addition to establishing an immunosuppressive shield around the tumor cell." (PMID 33256089, 2020). "This interaction of inhibition of angiogenesis with immune response has also been shown in patients with renal cell cancer and melanoma, in whom the addition of bevacizumab to anti-programmed death ligand 1 (anti-PD-L1) or anti-CTLA4 therapy increased the T cell response." (PMID 32205863, 2020).
melanoma (continued). "Ipilimumab, an anti-CTLA-4 monoclonal antibody, leading to depletion of regulatory T cells, resulted in clinical efficacy in melanoma patients in an Fc-mediated manner, which may be partly due to relieved NK cell cytotoxicity suppressed by Tregs." (PMID 32117298, 2020). "However, when melanoma is present in the brain before or at ISV + α-CTLA-4 treatment, this regimen cannot inhibit tumor growth in the brain." (PMID 32690669, 2020). "It was shown that the anti-CTLA-4 antibodies, currently used for the treatment of melanoma and lung cancer patients, significantly reduce the numbers of Tregs, and it is discussed if this is the mechanism how they actually activate the anti-tumor immune response." (PMID 32226027, 2020). "Combinatorial anti-tumor efficacy of ipilimumab (anti-CTLA-4) and nivolumab (anti-PD-1) in advanced stage melanoma and renal cell carcinoma (RCC) highlights the importance of targeting multiple immune pathways to unleash a more robust anti-tumor immune response." (PMID 32849557, 2020). "For example, patients in TCGA melanoma cohort were treated by diverse strategies, including anti-PD-1, anti-CTLA4, and cytokine tumor vaccine, which may have obscured associations between the lncRNA score and specific types of immunotherapy." (PMID 32259264, 2020). "Indeed, low levels of sPD-L1 at baseline correlated with a better clinical benefit of NSCLC patients treated with anti-PD-1 mAb and with a longer time before the progression of disease in melanoma patients treated with the anti-CTLA-4 mAb ipilimumab." (PMID 32033266, 2020). "In another two cohorts, a total of two patients (study IDs were CR4880 and PR4092,) with melanoma who received anti‐CTLA4 therapy and one patient with lung adenocarcinoma (study ID was DI6359,) who received anti‐PD‐1 therapy were verified to harbor PRKDC mutations." (PMID 32502294, 2020). "For instance, the combination of PD-1 and CTLA-4 antibody has been used for melanoma immunotherapy." (PMID 34138136, 2020). "Notably, in the subgroup analysis of monotherapy and combination ICI treatment, only in the anti‐cytotoxic‐T‐lymphocyte‐associated antigen 4 (anti‐CTLA4) group, patients with TERT mutations had a better prognosis, especially for melanoma." (PMID 32810393, 2020). "Furthermore, EZH2 inhibition can increase the cytotoxicity of human effector T cells in vitro and improve the efficacy of anti-CTLA-4 therapy in murine bladder cancer and melanoma as anti-CTLA-4 increases the expression of EZH2 in peripheral T cells." (PMID 32723346, 2020). "Convincing clinical evidence of synergy from CTLA-4/PD-1 co-inhibition in melanoma, kidney cancer and NSCLC has led to the understanding that concurrent targeting of multiple immune checkpoints leads to an increased magnitude and depth of anti-tumour immune responses across malignancies." (PMID 32157213, 2020). "Therefore, we conducted the TIDE algorithm and subclass mapping to compare the expression profile of the two subgroups and another published dataset containing 47 patients with melanoma that responded to immune checkpoint inhibitors (CTLA-4 and PD-1)." (PMID 33665205, 2020). "We hypothesized that mice rendered disease-free by ISV + α-CTLA-4 rejected intracranial re-engraftment with melanoma because of an adaptive antitumor T cell memory response." (PMID 32690669, 2020). "In addition, data obtained from melanoma samples and peripheral blood from patients treated with anti-CTLA-4 and anti-PD-1 revealed that treatment-specific effects can be observed." (PMID 32265933, 2020). "S100B could also serve as a strong baseline marker of OS in patients with melanoma receiving anti-CTLA4 and/or anti-PD-1 antibodies." (PMID 32295074, 2020). "Our in vivo studies showed that SB-3CT, an MMP2/9 inhibitor, could improve the efficacy of anti-PD-1 and anti-CTLA4 treatment in mouse models with melanoma and lung cancer, as well as metastatic melanoma in the lung." (PMID 32988398, 2020).
melanoma (continued). "Pseudoprogression could be observed in patients with advanced melanoma treated with CTLA-4 inhibitor or PD-1 inhibitor." (PMID 32984000, 2020). "In addition to PD-1, another immune checkpoint inhibitor, cytotoxic T-lymphocyte antigen 4 (CTLA-4), is important in melanoma." (PMID 32092958, 2020). "In this study, we employed quantitative multiparameter flow cytometry to assess expression of antigen-presenting molecules MHC-I and MHC-II on melanoma cells in pre-treatment biopsies from patients subsequently receiving anti-PD-1 or combination (anti-PD-1 plus anti-CTLA-4) immunotherapy." (PMID 33202676, 2020). "In another meta-analysis of a large number of melanoma and NSCLC patients treated with ICIs, both PFS and OS were significantly longer in male patients than in female patients, and this difference was more pronounced in melanoma patients and anti-CTLA-4 antibodies." (PMID 32864131, 2020). "Expression of IDO1, PD-L1 and CTLA-4 in PBMCs of melanoma patients have been shown to be associated with a negative outcome, independently from disease stage." (PMID 32793228, 2020). "High neutrophil/lymphocyte ratio (NLR), which is typically measured in conventional blood tests, is associated with poor prognosis in cytotoxic T lymphocyte antigen-4 (CTLA-4) antibody-treated patients with malignant melanoma and in PD-1 antibody-treated patients with various cancer." (PMID 31900651, 2020). "In addition, IFN-γ-induced IDO expression is increased in melanoma patients responding to CTLA-4 and PD-L1 blockade." (PMID 31968651, 2020). "HTA V.2.0 was used for gene expression profiling to allow analysis of coding as well as non-coding and alternatively spliced transcripts in peripheral T cells isolated from patients with melanoma treated with anti-PD-1, anti-CTLA-4, and combinations of both antibodies." (PMID 33268350, 2020). "The ADCC responses we observed in this study are in concordance with a previously published macaque study that demonstrated that CTLA-4 blocking antibodies could improve ADCC activity when used in combination with a melanoma vaccine." (PMID 32517277, 2020). "Using this framework and pretreatment RNA-Seq or NanoString tumor expression profiling, they have identified that TIDE more accurately predicts the outcome of melanoma patients treated with first-line anti-PD-1 or anti-CTLA-4 than other biomarkers such as PD-L1 levels and TMB." (PMID 32864131, 2020). "In order to assess for a humoral memory response, we collected serum from mice cured of B78 melanoma by an RT + IT-IC + anti-CTLA-4 in situ vaccine regimen and subsequently demonstrated immune memory by rejection of subcutaneous re-engraftment of B78 cells 90 days after treatment." (PMID 32849544, 2020). "A whole-exome sequencing (WES) of baseline tumor biopsies from 64 melanoma patients receiving CTLA-4 inhibitors (ipilimumab or tremelimumab) revealed over 100 somatic mutations related to a degree of clinical benefit within 6 months of therapy in responding patients (p = 0.01)." (PMID 32992737, 2020). "Various bacterial species have been indicated as potential biomarkers of anti-PD-1 or anti-CTLA-4 therapy efficacy in melanoma, next to biomarkers related to molecular and genetic tumor characteristics or the host immunological response, which are detected in patients’ blood." (PMID 32992737, 2020). "For example, multiple therapeutic antibodies that block immune checkpoints, such as cytotoxic T lymphocyte associated antigen 4 (CTLA4) and programmed cell death protein 1 (PD1), showed great effects in treating non-small-cell lung cancer, kidney cancer, and melanoma." (PMID 32974146, 2020). "Furthermore, detailed characterization of melanoma patients who are sensitive to immune checkpoint therapy would improve response rates and survival outcomes for future patients, given anti-CTLA-4/anti-PD-1/anti-PD-L1 antibodies." (PMID 33256089, 2020).